COPS9 (COP9 signalosome subunit 9)
Description:
[Isoform 1]: Component of the COP9 signalosome complex (CSN), a complex involved in various cellular and developmental processes. The CSN complex is an essential regulator of the ubiquitin (Ubl) conjugation pathway by mediating the deneddylation of the cullin subunits of SCF-type E3 ligase complexes, leading to decrease the Ubl ligase activity of SCF-type complexes such as SCF, CSA or DDB2. Plays a role in cell proliferation. [Isoform 2]: Negatively regulates neddylation of proteins, including ribosoaml protein RPL11.
Synonyms: CSNAP; MYEOV2
Tractability: No criterion of Open Targets' tractability assessment is met for any kind of drug.
Gene: Protein-coding gene on chromosome 2 (240,126,563 to 240,136,807, reverse strand). Ensembl gene ENSG00000172428.
Subcellular location: Nucleus (Isoform 1); Cytoplasm; Nucleus, nucleoplasm; Nucleus, nucleoplasm (Isoform 2)
Subcellular location (Human Protein Atlas): Cytosol; Nucleoplasm
Gene Ontology:
Molecular function: protein binding
Biological process: cellular response to UV; positive regulation of cell population proliferation
Cellular component: chromatin; COP9 signalosome; cytoplasm; nucleoplasm; nucleus
Genetic constraint (gnomAD): Loss-of-function variants: 8 observed, 6.8 expected, observed/expected ratio (o/e) 1.18, 90% interval 0.68 to 1.85. That is too few expected variants to judge how well the gene tolerates losing a copy. Missense variants: 74 observed, 73.14 expected, observed/expected ratio (o/e) 1.01, 90% interval 0.84 to 1.23. Synonymous variants: 39 observed, 27.55 expected, observed/expected ratio (o/e) 1.42, 90% interval 1.09 to 1.82.
Homologues: Orthologues: chimpanzee COPS9 (98% identical), pig COPS9 (98% identical), tropical clawed frog cops9 (98% identical), guinea pig COPS9 (96% identical), zebrafish cops9 (96% identical), Drosophila melanogaster CG17059 (63% identical).
Diseases named in the same sentence as COPS9 in open-access papers:
COPS9 is named in the same sentence as 5 diseases in open-access papers, as found by Europe PMC text mining. Sharing a sentence is not in itself a finding about the gene and the disease. The quoted sentences say what the papers report.
cancer (3 papers, 2013 to 2024). A tumor composed of atypical neoplastic, often pleomorphic cells that invade other tissues. "Therefore, aberrant overexpression of COPS6/COPS9 in HCC cells facilitated cancer cell growth, which may be attributed to the ubiquitination and degradation of p18 and p21." (PMID 38466642, 2024).
tumor (1 paper, 2024). "Both COPS6 and COPS9 knockdown also reduced viable HCC cell number after several days in culture as estimated by CCK8 assay, while overexpression significantly increased, suggesting that COPS6 and COPS9 accelerate HCC tumor growth." (PMID 38466642, 2024).
COPS9 also shares sentences with these, for which no sentence is quoted: multiple myeloma (1 paper); neurodevelopmental disorder (1); plasmacytoma (1).